IDO2 (indoleamine 2,3-dioxygenase 2)
Description:
Catalyzes the first and rate limiting step of the catabolism of the essential amino acid tryptophan along the kynurenine pathway. Involved in immune regulation. May not play a significant role in tryptophan-related tumoral resistance.
Synonyms: INDOL1
Tractability: Small molecule: a high-quality ligand is known. PROTAC: a small molecule that binds it is known.
Target class: Enzyme; Oxidoreductase
Gene: Protein-coding gene on chromosome 8 (39,934,614 to 40,016,392, forward strand). Ensembl gene ENSG00000188676.
Subcellular location (Human Protein Atlas): Cytosol
Pathways (Reactome):
Metabolism: Tryptophan catabolism
Gene Ontology:
Molecular function: indoleamine 2,3-dioxygenase activity; L-tryptophan 2,3-dioxygenase activity; heme binding; metal ion binding
Biological process: L-tryptophan catabolic process; 'de novo' NAD+ biosynthetic process from L-tryptophan
Cellular component: cytoplasm; cytosol
Genetic constraint (gnomAD): Loss-of-function variants: 16 observed, 19.35 expected, observed/expected ratio (o/e) 0.83, 90% interval 0.56 to 1.26. The upper end of that interval is the gene's LOEUF score, 1.26, which puts it in group 5 of 6, group 1 being the genes least tolerant of losing a copy. Missense variants: 352 observed, 311.43 expected, observed/expected ratio (o/e) 1.13, 90% interval 1.03 to 1.24. Synonymous variants: 146 observed, 120.63 expected, observed/expected ratio (o/e) 1.21, 90% interval 1.06 to 1.39.
Homologues: Orthologues: macaque IDO2 (95% identical), chimpanzee IDO2 (91% identical), dog IDO2 (79% identical), pig IDO2 (78% identical), rabbit IDO2 (78% identical), rat Ido2 (74% identical), mouse Ido2 (72% identical), guinea pig IDO2 (68% identical).
Diseases named in the same sentence as IDO2 in open-access papers:
IDO2 is named in the same sentence as 99 diseases in open-access papers, as found by Europe PMC text mining. Sharing a sentence is not in itself a finding about the gene and the disease. The quoted sentences say what the papers report.
Arthritis (14 papers, 2014 to 2025). Inflammation of a joint. "This reduction in arthritis was associated with a decrease in autoantibody secreting cells in IDO2 ko mice." (PMID 35493480, 2022). "IDO2-deficient mice showed a delayed onset and reduced arthritis severity, due to a reduction in pathogenic antibody-secreting cells and corresponding decrease in autoantibodies." (PMID 33968089, 2021). "IDO1 and IDO2 are functional interacting partners and have been associated to various autoimmune states, such as colitis, arthritis and encephalomyelitis." (PMID 29510755, 2018). "It has been demonstrated that IDO2 knockout inhibits the production of autoantibodies and alleviates symptoms in arthritis models, suggesting that IDO2 acts as a pro-inflammatory mediator directly within B cells, while IDO1 has markedly different functions." (PMID 39880074, 2025). "Using a series of adoptive transfer experiments, IDO2 in B cells was shown to be both necessary and sufficient for arthritis development." (PMID 35493480, 2022). "A recent study from our group examined the effect of enzymatically inactive IDO2 on the development of arthritis and contact hypersensitivity (CHS)." (PMID 35493480, 2022). "Our lab has developed an anti-IDO2 antibody that can successfully ameliorate arthritis in the KRN and CIA models." (PMID 35493480, 2022). "The differing roles of IDO1 and IDO2 in these different model systems of arthritis underscore the importance of using genetic knockouts or specific inhibitors of the individual IDO enzymes to properly assess IDO1 and IDO2 function." (PMID 35493480, 2022). "Like genetic knockouts or the anti-IDO2 antibody, targeting of IDO2 in B cells by this siRNA approach successfully reduces arthritis." (PMID 35493480, 2022). "Regarding IDO-2, IDO2 mediates the autoreactive B cell response driving arthritis through an IDO1-independent mechanism." (PMID 35918736, 2022). "The administration of IDO2-specific autoantibodies alleviated arthritis in two independent preclinical arthritis models, reducing autoreactive T and B cells activation." (PMID 34576041, 2021). "Using the dko mice together with the KRN model of arthritis, we demonstrate that IDO2 mediates the autoreactive B cell response driving arthritis through an IDO1-independent mechanism." (PMID 32973768, 2020). "Here, we find that autoantibody levels and arthritis were also reduced in IDO1/IDO2 dko mice, confirming that IDO2 mediates autoreactive B cell responses in an IDO1-independent manner." (PMID 32973768, 2020). "It has recently been shown that IDO2-specific monoclonal antibodies reduced auto reactive T and B cell activation and alleviated arthritis in two independent preclinical arthritis models." (PMID 29510755, 2018). "In the KRN model of spontaneous RA, we found that IDO2 was crucial for the development of arthritis but that IDO1 was completely dispensable." (PMID 25477879, 2014). "However, IDO2 activity has induced an inflammatory response in an arthritis mouse model and was protective in a psoriasis mouse model." (PMID 37226257, 2023). "Importantly, this proinflammatory effect of IDO2 on arthritis development was attributed specifically to its action in B cells." (PMID 35493480, 2022). "While CHS is reduced in mice carrying the catalytically inactive IDO2, arthritis is unaffected." (PMID 35493480, 2022). "In the same way, the anti-IDO2 3DNA formulation ameliorates arthritis in a preclinical model." (PMID 34576041, 2021). "In the same experimental setting, the specific silencing of IDO2 in B cells significantly reduced total arthritis severity, confirming the role of IDO2 in disease initiation and progression and pinpointing IDO2 as an innovative target for the treatment of this autoimmune disease." (PMID 33968089, 2021). "Serum transfer arthritis is modified in Indoleamine 2,3‐dioxygenase 2 (Ido2) mutant mice, suggesting that still to be identified endogenous tryptophan metabolites might account for this observation." (PMID 33734594, 2021).
Arthritis (continued). "However, the reduced arthritis in IDO2 ko mice could be due to alterations in the expression or activity of IDO1 in the mice." (PMID 32973768, 2020). "In RA, tryptophan is the substrate of indoleamine-2,3-dioxygenase IDO2, which was demonstrated to be required for the activation of CD4+ Th cells, the production of pathogenic autoantibodies, and the subsequent development of arthritis in a KRN mouse model of arthritis." (PMID 32235564, 2020). "Like the KRN model, development of arthritis in the CIA model is mediated by autoantibodies, though the specific effect of IDO1 and IDO2 on the B cell compartment remains to be established." (PMID 35493480, 2022). "Here, IDO2 ko mice were found to have enhanced disease, suggesting an anti-inflammatory role for IDO2 in this context, in contrast to the proinflammatory role of IDO2 in KRN arthritis." (PMID 35493480, 2022). "In a series of B cell add-back experiments similar to what was performed in the KRN arthritis model, addition of wild-type but not IDO2 ko B cells to the IDO2 genetic knockouts sensitized with oxazolone can restore a CHS response." (PMID 35493480, 2022). "Tryptophan, which is a substrate for the enzyme indoleamine-2,3-dioxygenase (IDO2), has been shown to be necessary for the activation of CD4+ T cells and autoantibodies production and may play a role in the development of mice models of arthritis." (PMID 35629898, 2022). "Importantly, B cell add-back experiments demonstrate the importance of this non-enzymatic role of IDO2 in B cells in arthritis, with enzymatically inactive IDO2-expressing B cells able to rescue arthritis in an otherwise IDO2 knockout system." (PMID 35493480, 2022). "Arthritis in dko KRN.g7 mice was indistinguishable from that in IDO2 ko KRN.g7 mice." (PMID 32973768, 2020). "However, in DC from arthritis patients, circulating DC expressed both IDO1 and IDO2." (PMID 25477879, 2014). "Confirming that this effect wasn’t due to alterations in the expression of IDO1 following deletion of IDO2, double knockout mice lacking both IDO1 and IDO2 show the same reduction in arthritis as is seen in IDO2 knockouts alone." (PMID 35493480, 2022). "A thorough analysis of the IDO2 involvement in the pathogenesis of arthritis revealed that IDO2 participates in the initiation stage of the response prior to the generation of autoantibodies; however, no clues for the exact mechanism of action of IDO2 could be obtained." (PMID 33968089, 2021). "This indicates that absence of IDO2 alone, independent of the presence or absence of IDO1 expression, was responsible for the reduced autoreactive B cell response and alleviation of arthritis in the IDO2 ko mice." (PMID 32973768, 2020).
melanoma (11 papers, 2012 to 2025). A malignant, usually aggressive tumor composed of atypical, neoplastic melanocytes. "Strikingly, IDO1, along with other kynurenine pathway genes previously targeted in melanoma (IDO2 and TDO2), also correlated with better outcomes in SKCM.met." (PMID 40427178, 2025). "Silencing IDO2 with siRNA inhibits melanoma cell growth, induces G1 phase cell cycle arrest, and promotes apoptosis." (PMID 40103267, 2025). "In summary, for the first time, this study demonstrates direct evidence of physiological and pathophysiological effects of IDO2 on B16 melanoma." (PMID 27058624, 2016). "We also evaluate the potential therapeutic effect of IDO2 siRNA and shRNA in a murine melanoma model." (PMID 27058624, 2016). "The data indicate increased Trp metabolism by TDO, IDO1, and IDO2 enzymes both in the direction of NAD+ synthesis and in the direction of KYNA branching in melanoma patients." (PMID 36012419, 2022). "Because these data do not take the complexity of the alternative splicing of IDO2 transcripts into consideration, we verified the absence of IDO2-matched RNA-Seq reads in 20 melanoma metastases sequenced in our laboratory (data not shown)." (PMID 25691885, 2015). "The murine melanoma cell line B16-BL6 showed strong expression of IDO2 without IFN-γ." (PMID 27058624, 2016). "At least, we did not observe killing of three different IDO2+ melanoma cell lines." (PMID 22388712, 2012). "This might suggest that even the high mutation burden subset of melanoma, which shows over-expression of both IDO-1 and IDO-2 but not TDO-2, does not respond to IDO-1 inhibitors and over-expression of all three genes are necessary for response to IDO-1 inhibitors." (PMID 34367262, 2021). "However, IDO2-specific T cells did not seem to kill melanoma cells although they expressed IDO2." (PMID 22388712, 2012). "As an isoenzyme, IDO2 has no confirmed pro‐angiogenic role, whereas TDO has been observed in the neovasculature of liver cancer, glioblastoma, melanoma, and bladder cancer." (PMID 40103267, 2025). "We recently observed that cells in the invasive melanoma cell line, B16-BL6, highly express IDO2 whereas the less invasive melanoma cell line, B16F10, had limited expression of IDO2 in the absence of interferon-gamma (IFN-γ) induction." (PMID 27058624, 2016).
autoimmune disease (9 papers, 2014 to 2025). A disorder resulting from loss of function or tissue destruction of an organ or multiple organs, arising from humoral or cellular immune responses of the individual to their own tissue constituents. "Consequently, it is critical to elucidate the detailed mechanisms and distinguish the individual contribution of IDO1 vs. IDO2 in cancer and/or autoimmune diseases." (PMID 37408267, 2023). "Although in some murine models IDO2 has been associated with a potential pro-inflammatory role, particularly in autoimmune diseases, other authors showed that IDO2 contributions to inflammation, both in the context of cancer and autoimmune disorders, remains to be elucidated." (PMID 32536910, 2020). "A substantial body of evidence has prompted the concept that IDO2 might act as a pro-inflammatory mediator in autoimmune diseases, specifically autoimmune arthritis, systemic lupus erythematosus and in contact hypersensitivity." (PMID 31134053, 2019). "However, compared to IDO1, in vivo studies demonstrated a contrasting role for IDO2, with experiments in preclinical models of autoimmune arthritis establishing a proinflammatory role for IDO2 in mediating B and T cell activation driving autoimmune disease." (PMID 32973768, 2020). "IDO2 shows little or no tryptophan catabolic activity and exerts contrasting immunomodulatory roles in a context-dependent manner in cancer and autoimmune diseases." (PMID 38003426, 2023).
Autoimmunity (9 papers, 2014 to 2023). The occurrence of an immune reaction against the organism's own cells or tissues. "IDO2 knockout mice display decreased joint inflammation, reduction the autoreactive B cells, and lower pathogenic autoantibodies levels compared to wild-type mice, indicating pathogenic IDO2 function in autoantibody-mediated autoimmunity." (PMID 34576041, 2021). "A previous study demonstrated that IDO2 functions as a modifier in B cells to control pathogenic inflammation and autoimmunity." (PMID 32944235, 2020). "Thus, IDO2 seems to be the dominant player in the pathogenic autoantibody-mediated autoimmunity through an IDO1-independent mechanism." (PMID 34576041, 2021). "As Ido2 function is associated with the development of severe rheumatoid arthritis symptoms, Gal-9’s ability to enhance Ido2 expression may promote the development or severity of symptoms of rheumatoid arthritis or other autoimmune conditions." (PMID 27799931, 2016). "IDO2 is crucial for autoantibody production and autoimmunity, and it activates B cells to regulate T-cell function." (PMID 35045867, 2022). "Our work shows a clear connection between IDO2 and B cell-mediated autoimmunity, however, the molecular mechanism by which IDO2 directs autoimmune and other inflammatory B cell responses is not known." (PMID 32973768, 2020). "Indoleamine 2,3-dioxygenase 2 encoded by IDO2 is an immunomodulatory molecule with potential effects on various diseases including cancer and autoimmune conditions." (PMID 32944235, 2020). "In contrast, IDO2 has been shown to play a pro-inflammatory role in the development of B cell-mediated autoimmunity." (PMID 32973768, 2020). "In contrast, anti-PR8 Ig titers were consistently lower in IDO2 ko and dko B6 mice, signifying that IDO2 plays an important role in immune responses outside of the context of autoimmunity." (PMID 32973768, 2020). "Recent studies reported that IDO2 may play an important role in diseases such as autoimmunity and cancer." (PMID 37408267, 2023). "Although IDO2 is more narrowly expressed and less active than IDO1, IDO2 and its SNPs may also play important inhibitory roles in autoimmunity." (PMID 35045867, 2022). "The recent in vivo studies performed on the models of autoimmunity suggest that IDO2 may play a distinct from IDO1 role in the B cell-mediated autoimmunity." (PMID 34576041, 2021). "As a matter of fact, it is partly already known how IDO2 could be involved in B cell-mediated autoimmunity and may also influence Treg activation." (PMID 32536910, 2020). "Taken together, IDO1 and IDO2 appear to play opposing roles in inflammatory immune responses, with IDO1 an important inhibitor of effector T cell-mediated responses, especially in the context of cancer, and IDO2 a critical proinflammatory mediator of B cell-mediated autoimmunity." (PMID 32973768, 2020). "Thus, further characterization of the synergy between IFNγ and Gal-9 during the induction of Ido1 and Ido2 is important to our understanding the pathophysiology of autoimmune disorders such as MS, Hashimoto’s disease, or rheumatoid arthritis." (PMID 27799931, 2016). "In Ido2-deficient mice, we found that genetic ablation of IDO2 but not IDO1 could phenocopy the effect of D-1MT in the context of the KRN model of RA autoimmunity." (PMID 25477879, 2014). "Thus, while 1MT has been used widely to implicate tryptophan catabolism in numerous chronic inflammatory pathologies, such as cancer, chronic infection, allergy, neurological disorders, and autoimmunity, the possible contributions of IDO2 in interpreting the effects of 1MT may be impactful." (PMID 25477879, 2014). "Recent studies indicate that IDO2 exerts an additional, non-enzymatic function and pro-inflammatory activity, which may play an important role in diseases such as autoimmunity and cancer." (PMID 37408267, 2023).
Autoimmunity (continued). "Our previous work demonstrated reduced autoreactive B and T cell responses and attenuated disease in IDO2 ko, but not IDO1 ko, KRN.g7 mice, suggesting that IDO2 was an important mediator of both B and T cell responses driving autoimmunity." (PMID 32973768, 2020). "We suggest that IDO2 may act in a distinct manner from IDO1 as a set-point for tolerance to “altered-self” antigens along the self-non-self continuum where immune challenges from cancer and autoimmunity may arise." (PMID 25477879, 2014).